CXCR4 (C-X-C motif chemokine receptor 4)
Diseases named in the same sentence as CXCR4 in open-access papers (continued):
Sharing a sentence is not in itself a finding about the gene and the disease.
pancreatic cancer (continued). "In this study, we demonstrated that the block of CXCR4 could not only decrease pancreatic cancer cell growth, but also increase sub-G1 apoptotic compartment, prolong the G0–G1 cycle and reduce the G2 and S phase." (PMID 19002187, 2008). "CXCR4 was a promising marker for pancreatic cancer progression." (PMID 19002187, 2008). "Recently, it was shown that the phosphorylation of CXCR4 at serine 339 may be a way to express the CXCR4 function on the cells, thus our data further confirmed that CXCR4 shRNA-transfected cells could effectively inhibit CXCR4 function in pancreatic cancers." (PMID 19002187, 2008). "Based on previous research on the central role of CXCR4 and the canonical Wnt pathway, we hypothesized that CXCR4 plays a role in the pancreatic cancer metastasis through the Wnt/β-catenin pathway." (PMID 19002187, 2008). "It was reported that CXCR4 was expressed at higher levels in pancreatic cancer cells and could influence the clinical outcome of PDA patients." (PMID 19002187, 2008). "In summary, genes associated with past alcohol consumption have been linked to physiological processes associated with increased risk for malignant transformation, pancreatic cancer cell proliferation, survival, invasion, metastasis, and impaired cell differentiation (K19, IFI27, S100P, CXCR4)." (PMID 17181856, 2006). "We hypothesized that HIPEC, with the use of gemcitabine after cytoreductive surgery, will decrease tumor progression of pancreatic cancer by reducing the residual neoplastic volume and PaCSCs subpopulation (EpCAM+CXCR4+CD133+), improving patient survival by reducing disease recurrence." (PMID 38730669, 2024). "CXCL12 stimulation also induces resistance to chemo- and radiotherapy by maintaining and stimulating CXCR4-expressing adhesive cancer cells in a protective microenvironment like the bone marrow, as has been recently confirmed for hematological malignancies and pancreatic cancer." (PMID 36725964, 2023). "According to report, anti-CXCR4 inhibitors could not only inhibit CXCR4 signaling and mobilize T cells of pancreatic cancer in vivo, but also illustrated higher anti-cancer effect if along with anti-PD-L1 drugs, exhibiting similar promising preclinical results." (PMID 35388021, 2022). "Whether Cxcr4 deficiency can increase activity of CXCR7 signaling in pancreatic cancer has not been analyzed." (PMID 35159011, 2022). "It has been suggested that the de novo methylation of the CXCR4 locus may simply be a part of genome-wide process in a distinct subgroup of pancreatic cancers characterized by a profound methylator phenotype and that alternative pathways to CXCR4/CXCL12 may be utilized for tumor progression." (PMID 34901003, 2021). "CXCR4 and ZEB1 expression is positively associated with the expression of CTLA-4 and PD-1, indicating that circ-UBAP2 might repress antigen presentation and promote immune escape in pancreatic cancer." (PMID 34496886, 2021). "Moreover, the HIF-1α/SDF-1/CXCR4 signaling pathway may be a potential therapeutic target for pancreatic cancer." (PMID 32362830, 2020). "Furthermore, expression of the CXCR4 ligand, CXCL12, by tumor-associated fibroblasts has been shown to promote immune evasion in a murine model of pancreatic cancer, while targeting CXCR4 with specific antagonist AMD3100 facilitated immunotherapy response in these model." (PMID 30873179, 2019). "Moreover, 73% of human pancreatic cancer tissues express both CXCR4 and ACKR3." (PMID 31275385, 2019). "Therefore, we examined whether the SDF-1/CXCR4 axis regulates the SATB-1 expression level in pancreatic cancer cells." (PMID 30337520, 2018). "However, CD133 expression combined with that of CXCR4, a mediator of cell migration, was also shown to enrich for a population that in addition to stem-like features, also displayed a metastatic potential in pancreatic cancer." (PMID 27457474, 2016).
pancreatic cancer (continued). "In addition, it is unclear whether and how the SDF-1/CXCR4 axis mediates PSC-induced chemoresistance in pancreatic cancer." (PMID 25609203, 2015). "Interestingly, pancreatic cancer is also highly dependent on CXCR4 to spread." (PMID 26389927, 2015). "However, there is evidence that CXCR-4 can induce de novo lymphangiogenesis and angiogenesis within the tumor or secondary site in pancreatic cancer, which may be favorable for lymphatic invasion." (PMID 24587996, 2014). "Further studies into metastatic mechanisms showed that SDF-1/CXCR-4 could modulate proliferation and progression of pancreatic cancer cells through CXCR-4-dependent activation of signal pathways, such as MAPK/ERK1/2, PI3K/Akt, FAK, Src, and STAT, which plays a core role in its devastating behavior." (PMID 24587996, 2014). "In addition, CXCR4 expression also correlated with stage in pancreatic cancer patients (P=0.05)." (PMID 23181100, 2012). "Moreover, the abrogation of CXCR4 could influence the pancreatic cancer cell phenotype including cell proliferation, colony formation, and cell invasion through the inhibition of canonical Wnt pathway." (PMID 19002187, 2008). "Notably, in vitro studies we observed that the abrogation of CXCR4 could obviously influence the pancreatic cancer cell phenotype including cell proliferation, colony formation, cell invasion and also inhibit the TOPflash activity." (PMID 19002187, 2008). "Interestingly, loss of SMAD4 in pancreatic cancer cells has been shown to shift TGFβ-triggered downstream cascades to mitogen-activated protein kinase (MAPK) and extracellular signal-regulated kinase (ERK) signaling, a pathway also known to be triggered upon CXCR4 activation." (PMID 39639824, 2025). "Clinical trials indicate that the CXCR4 inhibitor LY2510924 targets the CXCL12-CXCR4 axis, exhibits a favorable safety profile, and is well tolerated in patients with colorectal cancer, pancreatic cancer, and other solid tumors." (PMID 40109347, 2025). "There are some promising completed phase 1 clinical trials, such as NCT02695966 in pancreatic cancer and NCT02179970 in colorectal and pancreatic cancer targeting receptor CXCR4." (PMID 38791414, 2024). "In this previous rat model of our group, we observed a significant reduction of pancreatic cancer stem cells, which we determined by CD133+CXCR4+ labeling." (PMID 38730669, 2024). "In a mouse model of pancreatic cancer, FAP+ CAFs are the main source of CXCL12 that combines with CXCR4 on the surface of cancer cells and marginalized T cells through a CXCL12–CXCR4 signaling mechanism, leading to tumor immunosuppression." (PMID 37143134, 2023). "BMI1, ALDH1A1, CXCR4, EpCAM, OCT-4, c-MYC, and NESTIN are cancer stemness-related markers of pancreatic cancer." (PMID 35806187, 2022). "CXCL12, also known as stromal cell-derived factor 1 (SDF1), is a major ligand for CXCR4, and the CXCL12–CXCR4 axis promotes pancreatic cancer development, invasion, and metastasis." (PMID 36010986, 2022). "Targeting CXCR4 induces the mobilization of CD8+ T cells to the tumor nests and enhances the clinical response to immunotherapy in pancreatic cancer." (PMID 35954489, 2022). "First of all, we systematically evaluated the two putative pancreatic cancer stem cells phenotypes ESA+CD24+CD44+ and CXCR4+CD133+ in all cell lines." (PMID 36142575, 2022). "For example, TAFs in gastric cancer and pancreatic cancer secrete CXCL12 and activate the CXCL12/CXCR4-pathway to promote tumor growth 34,35." (PMID 35982904, 2022). "In this work, we evaluated the pancreatic cancer model cell line PANC-1for activation, internalization, and upregulation of CXCR4 following exposure to an activator, Isoproterenol." (PMID 35259193, 2022). "For example, the CXCL12/CXCR4 axis is involved in tumor growth, invasion, angiogenesis, and metastasis in CRC, breast and pancreatic cancers." (PMID 36703779, 2022).
pancreatic cancer (continued). "The CXCR4/CXCL12 axis seems to play an important role in the desmoplastic reaction characterizing PDAC, while CXCR3/CXCL10 resulted expressed in pancreatic tumor tissue, and their presence has been correlated with poor prognosis." (PMID 36142575, 2022). "Taken together, these clinical trials shed light on the importance of IL6, TGFβ, CXCR4, and CD40 in cancer treatment, as well as their potential therapeutic effects on pancreatic cancer." (PMID 35453676, 2022). "In pancreatic cancer, the lncRNA DLEU1 is overexpressed and targets miR‐381 to upregulate the expression of CXCR‐4, thereby aggravating the progression of pancreatic cancer." (PMID 35014178, 2022). "The relevance of some chemokine receptors, such as CX3CR1, CXCR4, and CXCR3, has been described in pancreatic cancer." (PMID 36142575, 2022). "Although the benefits of targeting IL6, TGFβ, CXCR4, and CD40 in pancreatic cancer remain elusive, clinical trials for these factors in other cancer types have shown promise." (PMID 35453676, 2022). "In this study, we developed a heterodimeric tracer 68Ga-yG5-RGD targeting both CXCR4 and integrin αvβ3, and evaluated its feasibility and utility in PET imaging of pancreatic cancer." (PMID 36145541, 2022). "In pancreatic cancer, evidence exists for changes toward a typical pro-inflammatory cytokine expression: in tissues higher MIF, IL-8, and CXCR-4 expression and reduced HLA-DR expression, and in serum higher IL-6 and IL-10 levels." (PMID 35034144, 2022). "By hindering the interaction of CXCR4-positive tumor cells with CXCL12-producing fibroblasts, AMD3100 therapy in a pancreatic cancer model induced rapid T-cell accumulation among cancer cells and acted synergistically with anti-PD-L1." (PMID 34575965, 2021). "CXCR4 also activates the Wnt and Hedgehog signalling pathways to express the EMT phenotype and promotes CXCL12-mediated pancreatic cancer cell invasion and metastasis." (PMID 34641806, 2021). "The expressions of C-X-C chemokine receptor type 4 (CXCR4) and cyclooxygenase-2 (COX-2) are increased after radiation therapy and facilitate metastasis of pancreatic cancer cells." (PMID 34836055, 2021). "In the pancreatic tumor microenvironment, CD8+ T cells were found to blockade PD-1 checkpoints and CXCR4 to exert an antitumor effect, suggested the promising objectives of immunotherapies." (PMID 35198564, 2021). "In pancreatic cancer, another study revealed that circ-UBAP2 and hsa-miR-494 can modulate the expression of CXCR4, HIF1A, ZEB1, and SDC1." (PMID 34496886, 2021). "The Oncomine (Life Technologies, Carlsbad, CA, USA) datasets indicate a high expression of CXCR4 mRNA in head and neck squamous cell carcinoma (HNSCC) and glioblastoma, breast, and pancreatic tumors compared to normal tissues." (PMID 32260318, 2020). "Due to the limited effect of a PD-1 inhibitor in pancreatic cancer, it is shown that CXC chemokine receptor 4 (CXCR4) blockade promotes T cell infiltration with its synergistic effect with PD-1 inhibitors in mouse models." (PMID 32823814, 2020). "We examined the role of HIF-1α, CXCR4, and SDF-1 protein in c-Myc regulation in pancreatic cancer cells." (PMID 32362830, 2020). "Evidence from recent work suggests that pancreatic cancer comprises several subsets of CSCs, including ESA+CD24+CD44+ cells, CD133+CXCR4+ cells, and c-Met+ subset cells, which are defined by their self-renewal ability, tumorigenicity, and metastatic ability." (PMID 28032597, 2017). "Pancreatic CSCs express specific markers, including CD24, CD44, CD133, EpCAM, CXCR4, c-Met, and CD166, at levels substantially different from the bulk pancreatic cancer cells." (PMID 28845161, 2017). "The chemokine CXCL12 binds the two receptors CXCR4 and CXCR7 and transduces on the mTOR pathway in pancreatic cancer, gastric cancer, T cell leukemia cell and in human renal cancer cells." (PMID 26934559, 2016).
pancreatic cancer (continued). "In pancreatic cancer, combination of two distinct expression patterns, such as of CD44/CD24 together with the epithelial-specific antigen (ESA) or CD133/CXCR4, can identify the cancer stem-like population." (PMID 27457474, 2016). "Several cell-surface markers, including CXCR4, ALDH, CD24 and CD44 have been used to identify of cancer stem-like cells in pancreatic cancer." (PMID 25811929, 2015). "SDF-1/CXCR4 and MMP-2 are overexpressed in pancreatic cancer tissues, and have been found to act as prognostic markers in various types of cancer, including pancreatic cancer." (PMID 26213494, 2015). "In pancreatic cancer concomitant expression of CD133 and CXCR4 identified a specific population of migrating cancer stem cells capable of evading the primary tumor and reaching distant sites." (PMID 26020117, 2015). "In vitro, we demonstrated that overexpression of Nodal promotes pancreatic cancer cell migration and invasion, induces EMT and enhances the expression of MMP2 and CXCR4." (PMID 25557170, 2015). "It has been reported that CXCL12/CXCR4 expression was significantly correlated with microvascular density (MVD)/microlymphatic vessel density (MLVD), and thus might be associated with angiogenesis/lymphangiogenesis and organ-specific metastasis in pancreatic cancer." (PMID 25679210, 2015). "Our in vivo and in vitro results demonstrated that activated primary PSC from pancreatic cancer tissues typically expressed high levels of SDF-1α, while high CXCR4 expression was typically observed in PCCs." (PMID 25609203, 2015). "T3M4 cells express CXCR4 as the majority of other pancreatic cancer cell lines and we also report that direct hyperglycemia and both types of PSC culture media exposures slightly increased the CXCR4 protein expression on T3M4 cells." (PMID 26010611, 2015). "The focus of this study was to determine the effects of GSK3β and investigate its molecular mechanism of action, specifically via the GSK3β-CXCR4/MMP-2 pathway, in PANC1 pancreatic cancer cells." (PMID 26213494, 2015). "To elucidate the effect of GSK3β on the expression of CXCR4 and MMP-2 in pancreatic cancer cells, we overexpresses GSK3β in PANC1 and SW-1990 cells." (PMID 26213494, 2015). "Here, we investigated the relationship between GSK3β and CXCR4/MMP-2 in pancreatic cancer cells, in order to further characterize the cellular and molecular mechanisms involved in pancreatic cancer." (PMID 26213494, 2015). "In our previous study, we found that SDF-1α/CXCR4 upregulated MMP-2 expression and induced the invasion of PANC1 and SW-1990 pancreatic cancer cells by activating p38 MAPK." (PMID 26213494, 2015). "In pancreatic cancer, CD133+CXCR4+ pancreatic CSC have EMT characteristics and invasiveness, which can be specifically blocked by a CXCR4 inhibitor." (PMID 25301732, 2014). "KMC14 cells expressed mRNA of Notch-1, Notch-2, Jagged-1, c-Met, CXCR-4, CD24 and CD44, except Jagged-2, that were reported as pancreatic cancer markers." (PMID 24278411, 2013). "CXCR4 and/or CXCL12 are up-regulated in pancreatic cancer, colon cancer, ovarian cancer, lymphoma, medulloblastoma and glioma, which suggests a critical role of CXCR4 in these cancers." (PMID 23555768, 2013). "They showed that in the invasive front of pancreatic tumors, a distinct subpopulation of CD133+CXCR4+ CSCs determined the metastatic phenotype of the individual tumor." (PMID 24133453, 2013). "Here, our objective was to investigate the roles of CXCR4 and CXCR7 in CXCL12-driven activation of the MAPK pathway in human pancreatic cancer cells." (PMID 22472349, 2012). "Markers for CSCs/SCs or pancreatic cancer, including S100P, OCT4, and CXCR4, were assessed in pancreaspheres." (PMID 22626610, 2012). "Similar observations were made in pancreatic cancer, where within the identified CD133+ CSC population, there existed two subpopulations based on CXCR4 expression, and only the CXCR4+ population was capable of metastasizing." (PMID 22295241, 2012).
pancreatic cancer (continued). "Our results suggest that both CXCR4 and CXCR7 are potential targets in the development of effective therapies to halt the growth of pancreatic cancer." (PMID 22472349, 2012). "The CXCR4/SDF-1 axis is known to be responsible for invasion and metastasis in pancreatic cancer, and is a hematopoietic stem cell marker." (PMID 22384257, 2012). "To assess the clinical frequency of CXCR4 and CXCR7 co-expression, we performed immunohistochemical (IHC) staining in 51 FFPE human pancreatic cancer specimens." (PMID 22472349, 2012). "In summary, we report that CXCR4 and CXCR7 are co-expressed with high frequency in human pancreatic cancer specimens and cell lines." (PMID 22472349, 2012). "Our results demonstrate that CXCR4 and CXCR7 are co-expressed with high frequency in human pancreatic cancers and that either receptor can regulate the MAPK pathway." (PMID 22472349, 2012). "CCE cells produced 3-fold more spheres than control cells and were more invasive, secreted more MMP-9, and overexpressed markers for pancreatic SCs/CSCs (i.e., CXCR4, OCT4, CD44) and S100P, a marker for pancreatic cancer." (PMID 22626610, 2012). "In summary, our data demonstrate that CXCR4 and CXCR7 are frequently co-expressed in human pancreatic cancer tissues and cell lines." (PMID 22472349, 2012). "Interactions between CXCR4 and its ligand, CXCL12, promote the survival of breast, pancreatic cancers, and melanoma." (PMID 21539750, 2011). "In a pancreatic cancer cell line, two distinct populations, namely CD133+CXCR4+ and CD133+CXCR4-, are both tumorigenic but only the former migratory cells cause metastasis." (PMID 24212622, 2011). "Effect of CXCR4 activation by CXCL12 on restricting the gemcitabine-induced cytotoxicity and stimulating the survival signalling was examined in pancreatic cancer cells by MTT, DNA laddering, caspase activity, immunoblot, and promoter-reporter assays." (PMID 21045835, 2010). "In a study aimed at identifying pancreatic CSCs in tissue samples derived from patients, it was demonstrated that at the invading front of pancreatic tumors, CSCs, as defined by the presence of CD133+, also expressed CXCR4." (PMID 24281215, 2010). "The CXCR4/CXCL12 system operates probably as a paracrine loop to enhance the malignancy of pancreatic cancer cells." (PMID 19352387, 2009). "CXCR4 is the predominant receptor for the chemokine ligand CXCL12; overexpression of CXCR4 and CXCL12 is found in several solid cancers, such as CRC, gastric cancer, pancreatic cancer and lung cancer." (PMID 38791414, 2024). "The CXCR4 antagonist motixafortide (BL-8040), which can inhibit the immunosuppressive CXCL12-CXCR4 axis driven by FAP + CAFs, is currently being investigated in phase II clinical trials involving pancreatic cancer patients in combination with pembrolizumab and/or chemotherapy (NCT02826486)." (PMID 37723510, 2023). "CXCR4 inhibitors have been shown to significantly improve the TME in pancreatic cancer and increase the sensitivity of tumors to immune checkpoint inhibitors, increasing the benefits of immunotherapy in pancreatic cancer." (PMID 36308553, 2023). "Its value in pancreatic cancer is yet to be determined, and it is known that PDAC contains a very important tumor-bound stromal component, so elucidating the relationship of the CXCR4 expression in the stroma and its involvement in PDAC is of particular interest." (PMID 37697316, 2023). "The interplay between CXCR4 and CXCR7 may be important in PDAC since CXCR4 and CXCR7 are often co-expressed in human pancreatic cancer cell lines and tissues." (PMID 35008248, 2021).